ENSG00000268173 (novel protein, readthrough between PIK3R2 and IFI30)
Gene: Protein-coding gene on chromosome 19 (18,153,158 to 18,178,117, forward strand). Ensembl gene ENSG00000268173.
Genetic constraint (gnomAD): Missense variants: 826 observed, 875.38 expected, observed/expected ratio (o/e) 0.94, 90% interval 0.89 to 1. Synonymous variants: 444 observed, 381.55 expected, observed/expected ratio (o/e) 1.16, 90% interval 1.08 to 1.26.